MTOR (mechanistic target of rapamycin kinase)
Diseases named in the same sentence as MTOR in open-access papers (continued):
Sharing a sentence is not in itself a finding about the gene and the disease.
cancer (continued). "Immunohistochemistry (IHC) results indicated that p-mTOR and p-S6K were significantly upregulated in carcinoma tissues, and significantly negatively correlated to NEDD4L." (PMID 35090513, 2022). "In Homo sapiens, missing phosphatase and tensin homologs of the phosphoinositide 3-kinase (PI3K)/AKT/mTOR signal transduction pathway on chromosome 10 are often activated in various carcinomas." (PMID 35082928, 2022). "According to a previous study, stimulation of mTOR signaling induces EMT to enhance the invading capacity of carcinoma cells." (PMID 36471885, 2022). "Our results showed that the cisplatin-induced the upregulation of BCAT1, which decreased the cisplatin sensitivity of cancer cells by facilitating autophagy via the Leu-mediated activation of the mTOR signaling pathway." (PMID 33568627, 2021). "Among these, up-regulation of the PI3K / AKT / mTOR pathway is one of the main pathways in many malignant tumors." (PMID 34604242, 2021). "Taken together, GLI1/2 mediates mTOR-induced PD-L1 expression to promote immune evasion of cancer cells, as well as promotes chemoresistance." (PMID 34572373, 2021). "As a secreted serine protease, KLK8 is known to mediate the proteolytic process of pro-EGF into mature EGF.EGF is known to activate PI3K/Akt/mTOR pathway in a variety of cancers." (PMID 34395235, 2021). "In recent years, there have been multiple efforts to focus on the development of mTOR inhibitors for cancer therapeutics." (PMID 34716294, 2021). "The regulation of mTOR signaling by Rab1A was reported by several studies in multiple types of cancers including CRC." (PMID 34376787, 2021). "It has been reported that excessive activation of the mTOR pathway and abnormal cell metabolism jointly lead to cancer occurrence." (PMID 34194607, 2021). "This activation of the MAPK/ERK pathway is indicative of a pro-survival feedback loop often observed with mTOR inhibition that can contribute to cancer recurrence." (PMID 34208071, 2021). "Based on this biological rationale, the anti-proliferative effect of mTOR pathway inhibition was identified as a promising therapeutic strategy in cancer and in NETs." (PMID 33916707, 2021). "Results from GSEA presented that several tumor-related pathways were enriched in the high-risk group, such as pathways in cancer, MAPK signaling pathway, VEGF signaling pathway, mTOR signaling pathway, and JAK signaling pathway." (PMID 33714257, 2021). "Available evidence also suggests that miR‐100 is down‐regulated in many human cancers including breast, bladder and lung, by regulating proliferation, differentiation, migration, invasion, and apoptosis due to targeting the mTOR pathway." (PMID 34118183, 2021). "Overall, these data show that targeted inhibition of mTOR signaling in cancer cells impedes tumor progression and metastatic outbreaks." (PMID 34608135, 2021). "The mTOR pathway involves in the regulation of protein synthesis, glucose metabolism, lipid metabolism, glutamine metabolism, and nucleotide synthesis in cancer cells." (PMID 35372372, 2021). "As the mTOR pathway is constitutively activated in cancer, levels of DEPTOR are low in most tumours." (PMID 34519269, 2021). "Although inhibition of mTOR pathway is being pursued to impair the viability of cancer cells, but current inhibitors of mTOR are limited by issues of potency and resistance." (PMID 33754064, 2021). "Dysregulation and activating mutations of mTOR have been reported in various types of human cancers, and hence mTOR inhibitors have been approved for the treatment of malignancies." (PMID 34712612, 2021). "EGFR is a major signal transducer of mitogens in cancer pathogenesis and progression upstream of mTOR and is an important target in anti-cancer therapies." (PMID 34361836, 2021).
cancer (continued). "Based on these findings, rapamycin, as an allosteric inhibitor of mTOR, was approved for the treatment of various cancers by forming a complex with FKBP12 to inhibit mTORC1 activity." (PMID 33582655, 2021). "Conversely, some types of cancers are treated with mTOR inhibitors to reduce tumor cell proliferation." (PMID 35008195, 2021). "According to previous findings, the PI3K/AKT/mTOR pathway governs cancer cell migration and invasion by regulating F-actin reorganization." (PMID 34279440, 2021). "A possible explanation for the role of PE_PGRS proteins on mTOR regulation is provided by cancer studies." (PMID 34346699, 2021). "mTOR, one of the most common downstream effectors of Akt, integrates many proteins to promote cancer progression." (PMID 34916492, 2021). "Several inhibitors of BET protein and mTOR signaling either alone or in combination with other target agents, are in multiple clinical trials in patients with advanced cancers." (PMID 34565342, 2021). "Downregulation of fatty acid synthesis has been found to trigger apoptosis via the Akt/mTOR/SREBP-1c signaling pathway in many cancer cell lines." (PMID 34343190, 2021). "Peg10 is a known oncogene and has been shown to interact with Nanog and Oct4 in human cancer cells, and Larp1 is thought to regulate translation downstream of the mTor pathway." (PMID 33863351, 2021). "Since mTOR is a global activator of tRNA transcription in cancer cells, we determined if this was also the case during CIS escape." (PMID 34928935, 2021). "PPT1 has been reported to be a critical regulator of cancer progression by its modulation of autophagy and mTOR signaling." (PMID 35004674, 2021). "The mTOR is a downstream molecule that can induce the invasion, migration, proliferation, and angiogenesis of cancer cells." (PMID 33802643, 2021). "Anomalous activation of PI3K/Akt/mTOR axis contributes to the unconstrained proliferation of cancer cells and is the most commonly occurring pathway anomalies involved in the maintenance and progression of numerous cancers." (PMID 34691211, 2021). "miR-873-5p affects cancer development through the PIK3/AKT/mTOR, Wnt/β-Catenin, NF-κβ, and MEK/ERK signaling pathways." (PMID 34676171, 2021). "Resveratrol was reported to induce autophagy by direct inhibition of mTOR-ULK1 pathway in an ATP-competitive way, and can kill MCF7 cells which are mTOR inhibitor sensitive, displaying anti-cancer potential." (PMID 34512368, 2021). "The PI3K/Akt/mTOR pathway is one of the most deregulated signaling cascades involved in the development of different human cancers." (PMID 34830339, 2021). "In contrast, the inhibition of mTOR signalling, such as rapamycin, temsirolimus or everolimus, significantly contributes to cancer prevention." (PMID 34416907, 2021). "To investigate the underlying mechanisms of the combinatorial effect of mTOR and TrxR inhibitor, we analyzed the expression of ER stress-related proteins in cancer cells after treated with mTOR inhibitors and auranofin." (PMID 33754064, 2021). "A variety of oncogenic functions like tumor invasion, angiogenesis, polarization of macrophages, immune suppression, and inflammation also involve PI3K/Akt/mTOR as a signaling pathway, thus making it an attractive target for cancer chemotherapy." (PMID 34439380, 2021). "PI3K is a key molecule in the PI3K/Akt/mTOR signalling pathway, which is involved in the regulation of a variety of transcription factors in cancer." (PMID 34741385, 2021). "Meanwhile, several studies have suggested that activation of mTOR signaling provides anti-cancer activity." (PMID 34265852, 2021). "Depletion of progranulin inhibited the proliferation and phosphorylation of the proteins in the Akt/mTOR signaling pathway in hematopoietic cancer cell lines similarly to other cancer cell types." (PMID 33490663, 2021). "MTOR can constitute two kinase complexes, mTORC1 and mTORC2, both of which play important roles in cancer." (PMID 35201498, 2021).
cancer (continued). "We show that mTOR and TrxR inhibitors synergize to induce cancer cell death by triggering oxidative stress." (PMID 33754064, 2021). "The importance of the mTOR pathway in cancer development further supported other bi-specific drug development programs, such as the dual mTOR/DNA-PK inhibitor, CC-115, or the PI3K/PDK1 inhibitor, NVP-BAG956." (PMID 33401428, 2021). "The phosphatidylinositol 3‐kinase (PI3K)/Akt/mammalian target of rapamycin (mTOR) pathway, one of the most commonly activated signalling pathways in many human cancers, is a key signalling pathway that controls cell growth, differentiation and metabolism." (PMID 33507584, 2021). "Based on the current research results, we first chose to study the expression level of mTOR pathway genes in cancer and their differential expression levels." (PMID 34194607, 2021). "The PI3K/Akt/mTOR pathway has been considered a major drug target due to its frequent hyperactivation in cancer." (PMID 34744708, 2021). "Contains possibly important somatic SNV/indels in selected KEGG pathways (namely “Cell cycle”, “mTOR signaling” and “Pathways in cancer”)." (PMID 33622343, 2021). "The PI3K/AKT/mTOR pathway is one of the most frequently activated pathways in several types of cancers." (PMID 33790792, 2021). "The overactivation of mTOR is observed in more than 70% of cancers, indicating its critical functions in tumorigenesis." (PMID 34094949, 2021). "There is no doubt that such trial will shed light on the immunostimulatory benefits of mTOR inhibitors in cancer patients and if successful, will set the stage for a new beginning for mTOR inhibitors in cancer therapy." (PMID 33802831, 2021). "Inhibition of the PI3K/Akt/mTOR signaling pathway has been investigated as a therapeutic target in cancer treatments." (PMID 34783291, 2021). "Metformin, a common antidiabetic agent, has been reported with potent anti-cancer benefits via regulating multiple signaling pathways in cancer cells, including mammalian target of rapamycin (mTOR) signaling pathway." (PMID 34334083, 2021). "Activation in mTOR signalling promotes increased metabolic flux and cell growth supporting cancer development progression and spread." (PMID 34283054, 2021). "MiR-101 is involved in several types of cancer development since it provides a downstream activation of mTOR signaling pathway, including mTORC2 and HIF-2α." (PMID 33918154, 2021). "Naringenin can induce cancer cell death by promoting autophagy and downregulate the Akt/mTOR signaling pathway." (PMID 33768214, 2021). "The phosphoinositide 3‐kinase (PI3K)/AKT/mTOR signal pathway is identified as one of the most commonly deregulated pathways in human cancers." (PMID 34431227, 2021). "DDIT4 was suitable candidate gene in order to predict miRNAs in CRC because of not only its participation in the PI3K/Akt/mTOR signaling pathway but also its involvement in “miRNAs in cancer” pathway as shown by KEGG pathway analysis." (PMID 34107956, 2021). "PI3K/AKT/mTOR pathway has pivotal role in tumor progression, drug resistance, and poor prognosis in various cancers." (PMID 37303943, 2021). "Rapamycin, a specific inhibitor of the mammalian target of rapamycin (mTOR), is already a useful cancer treatment choice, possibly via its effects on the immune system." (PMID 33897695, 2021). "An interesting point is that, according to studies, rapamycin can potentiate the anticancer properties that doxorubicin has and, when combined, can inhibit cancer cell growth and lead to cell death by impacting mTOR/p70S6K signalling." (PMID 33804163, 2021). "The AKT/mTOR pathway, a major downstream signaling activated by ROS production, has been shown to be frequently activated in several types of human cancers and prompted lipid synthesis through activating SREBP1/250." (PMID 33414447, 2021).
cancer (continued). "The PI3K/AKT/mTOR pathway is one of the most active cell survival pathways in cancer, often leading to chemoresistance." (PMID 34359640, 2021). "mTOR pathway is vital for modulating key cancer cell behaviors, including cell growth, proliferation, migration and survival, as well as apoptosis resistance, metabolism, and angiogenesis." (PMID 34615858, 2021). "The concurrent inhibition of GLI and PI3K/AKT/mTOR signaling demonstrated a synergistic effect in inhibiting in vivo cancer cell growth, evident by reduced tumor burden of xenografts compared to treatment with any of the agents alone." (PMID 34572373, 2021). "The mTOR is a highly conserved serine/threonine protein kinase that is central regulating essential cellular processes and mTOR inhibitors are used in cancer therapy." (PMID 33536086, 2021). "NMac24 significantly inhibits cancer cell proliferation, induces ATP depletion, decreases MMP and OCR, causes AMPK/mTOR/ERK signaling changes in addition to the dramatic mtROS elevation that were consistent results with NMac1." (PMID 34876614, 2021). "Activation of mTOR in immune cells and other cell types within the tumor microenvironment also affects cancer progression through supporting angiogenesis, metastasis, and drug resistance." (PMID 34208071, 2021). "Accumulated clinical evidence has shown that the mTOR inhibitors exhibit effective suppression effect against malignant tumours." (PMID 34120414, 2021). "The amino acid pool maintained by GLN in cancer cells is an important factor in the stimulation of mTOR signaling." (PMID 34503536, 2021). "The PI3K/Akt/mTOR pathway is genetically targeted in many kinds of tumours, and it is frequently activated as a cancer driver." (PMID 34495871, 2021). "For example, miR-149-5p, activated by circulating endogenous RNA circNRIP1, stimulates the PI3K/Akt/mTOR pathway to promote cancer cell growth." (PMID 33946927, 2021). "The mammalian target of rapamycin (mTOR) is known to be involved in regulation of cell survival, tumour progression, and anti-cancer drug resistance in many types of cancer, including CRC." (PMID 34708245, 2021). "Targeting the Akt/mTOR/p70S6K signaling pathway and actin reorganization are therefore promising approaches for attenuating cancer metastasis." (PMID 33758209, 2021). "Some researches have shown that ghrelin increases proliferation and metastasis in cancer cells through targeting PI3K/AKT/mTOR." (PMID 34122616, 2021). "In the past decades, we know that the characteristics of cancer include, etc., and the activation of mTOR signal is related to every cell carcinogenesis process, such as uncontrolled cell proliferation, escaping anti-tumor immunity and abnormal angiogenesis." (PMID 34737950, 2021). "Downregulation of Akt/PI3K expression results in the inactivation of mTOR and induction of autophagy in cancer cells." (PMID 34500742, 2021). "Our article is based on a literature search using Pubmed (search criteria “p62” and “autophagy”, “inflammasome”, “Nrf2”, “mTOR”, “NF-kappaB” or “cancer/HCC”)." (PMID 34206503, 2021). "PI3K-Akt-mTOR and AMPK signalling: Hyperactivation of PI3K-AKT-mTOR signalling is frequently observed in various cancers." (PMID 34680611, 2021). "Activation of PI3K/AKT/mTOR enhances tumor micro-vessel density and increases invasive potential of cancer cells." (PMID 34831287, 2021). "Cancer cells with an abnormally active PI3K/AKT/mTOR pathway have a higher propensity to proliferate aggressively, extending their survival period and becoming resistant to chemotherapy." (PMID 35153766, 2021). "The PI3K/AKT/mTOR pathway participates in cancer metastasis in which cancer cells are stimulated by the activation of RTKs, cytokines, or hormones." (PMID 34279440, 2021). "The aim of this review was to summarize current available information about the role of phosphatidylinositol-3-kinase (PI3K)/AKT/mammalian target of rapamycin (mTOR) signaling in cancer as a potential target for new therapy options." (PMID 33572326, 2021).
cancer (continued). "The PI3K/Akt/mTOR pathway is a master regulator of cancer progression and is considered as one of the most important therapeutic targets." (PMID 34830339, 2021). "Recent reports have shown that the inhibitors of AATs (JPH203 and V‐9302) effectively reduced the proliferation of different cancer cell types by inhibiting mTOR activation." (PMID 34003553, 2021). "The involvement of mTOR in regulating P-gp expression has been demonstrated in the context of cancer." (PMID 34421607, 2021). "The PI3K/AKT/mTOR pathway is considered a significant factor in the multidrug resistance (MDR) in a variety of cancers." (PMID 34315512, 2021). "Numerous natural products have been proved to suppress cancer cells by targeting the PI3K/AKT/mTOR-mediated autophagy." (PMID 33841067, 2021). "Constitutive activation of PI3K-Akt-mTOR axis is known to suppress autophagy and is a characteristic of cancer, by promoting the proliferation, growth, and survival of the tumor cells." (PMID 33628386, 2021). "Cardamonin has also been shown to inhibit cancer metastasis by suppressing the PI3K/AKT/mTOR pathway." (PMID 33530617, 2021). "We also observed that overexpressed Neu2 inhibited many molecules in the PI3K-Akt/mTOR pathway, which are aberrantly expressed during cancer progression." (PMID 33526785, 2021). "Everolimus, an inhibitor of mTOR, is used clinically at high doses for the treatment of some cancers, and at intermediate doses as an immunosuppressive agent for solid organ transplantation." (PMID 33740465, 2021). "A high expression of AMPK, mTOR, and 4EBP1 in tumors before treatment mediates the NACT effect in GC patients and is associated with tumor response to anti-cancer therapy." (PMID 34681840, 2021). "Our dynamical analysis suggests that the downregulation of KRAS, mTOR and autophagy are crucial in anti-cancer therapy." (PMID 33925206, 2021). "Even though there is research that reported that ERβ ligand was able to activate Akt to promote remyelination, several studies regarding cancer prevention or treatment demonstrated that activation of ERβ repressed the Akt/mTOR signaling pathway." (PMID 34836271, 2021). "We found that Leu treatment also promoted mTOR activation, reduced autophagy flux, and increased the cisplatin cytotoxicity to cancer cells." (PMID 33568627, 2021). "Metabolomic analysis revealed that HZJD altered a variety of metabolites, which revealed its role in the central carbon metabolism in cancer, the mTOR signaling pathway, and the choline metabolism in cancer." (PMID 33933119, 2021). "It is also worthy to note that glutaminolysis negatively regulates autophagy through mTOR activation, suggesting that autophagy and glutaminolysis can mutually modulate to promote cancer metabolism." (PMID 33535537, 2021). "Viewing mTOR as a widespread driver of therapeutic resistance suggests considerable hope for targeting cancer drug resistance using mTOR inhibitors." (PMID 34863080, 2021). "For example, hyperactivation of mammalian target of rapamycin (mTOR) has frequently been observed in numerous cancers." (PMID 33671514, 2021). "The limited success of Rapamycin as an anti-cancer drug led to the development of ATP competitive mTOR inhibitors such as Torin-2 30,31." (PMID 33390782, 2021). "The mTOR pathway was a classical signal transduction pathway regulating cell growth and metabolism, and was dysregulated in many cancers." (PMID 38650282, 2021). "It is reported that mTOR as a key activator of PKM2 is known augmented by mTOR activation and reduced by mTOR suppression in cancer cells." (PMID 34687136, 2021). "Many drugs inhibiting the mTOR pathway are used in cancer therapy, including temsirolimus, everolimus, and ridaforolimus." (PMID 33925400, 2021). "MTOR signalling is dysregulated in many cancers, promoting the cell proliferation and metabolism that contribute to tumour initiation and progression." (PMID 33864493, 2021).